XPO1 (exportin 1)
Diseases named in the same sentence as XPO1 in open-access papers (continued):
Sharing a sentence is not in itself a finding about the gene and the disease.
cancer (continued). "While XPO1 inhibition directly correlates with selinexor pharmacokinetics, the biological outcome of this inhibition depends on modulation of pathways downstream of XPO1, which ultimately determines cancer cell responsiveness." (PMID 26654943, 2016). "Several studies focused on patient samples have suggested that recurrent mutation of residue E571 located in the NES binding groove of XPO1 might have prognostic or therapeutic value for different types of cancer." (PMID 27634897, 2016). "When we first developed the XPO1 occupancy assay, we hypothesized that this assay would explain the difference in cancer cell sensitivity to selinexor observed in cytotoxicity assays." (PMID 26654943, 2016). "The contribution of CA IX and its complexes with XPO1 to such responses may reveal novel mechanisms in cell and cancer biology." (PMID 25793203, 2015). "Use of XPO-1 inhibition in cancer therapy has been met with limited success." (PMID 26620414, 2015). "Multiple tumor suppressor proteins are mislocalized in cancer cells by overexpressed XPO-1." (PMID 26620414, 2015). "Interestingly, XPO1 inhibition appears to have selective effects primarily on cancer cells, while sparing normal cells in most cases." (PMID 24503695, 2014). "Furthermore, overexpression of XPO1 correlates with a poor prognosis in many human cancers, indicating that changes in nuclear-cytoplasmic trafficking resulting in aberrant localization of key proteins can contribute to cancer development and progression." (PMID 25022346, 2014). "Importantly, elevated XPO1 expression is generally correlated with poor prognosis in these cancers, as well as in osterosarcoma and ovarian cancer." (PMID 25057921, 2014). "Nuclear export through XPO1 is up-regulated in different cancer types and may be used as prognostic indicator." (PMID 25476752, 2014). "If this relocation process is inhibited in cancer, cytoplasmic XPO1 will accumulate and more XPO1 might get incorporated in exosomes." (PMID 24391718, 2013). "XPO1 has been suggested as a prognostic marker for other types of cancer." (PMID 24391718, 2013). "Consequently, XPO1 has garnered attention as a potential therapeutic target in cancer treatment." (PMID 39882192, 2025). "The targets of ICIs approved for cancer treatment are PD-1/programmed death ligand 1 (PD-L1), cytotoxic T-lymphocyte associated protein 4 (CTLA-4), and lymphocyte activation gene-3 (LAG-3), and XPO1 inhibition has been shown to modulate the expression of these molecules." (PMID 40291981, 2025). "Combining nuclear pore inhibition, specifically targeting either the structural components of the nuclear pore complex (NPC) or the inhibition of nuclear export via XPO1 (exportin 1), with other established cancer therapies such as chemotherapy or immunotherapy could enhance treatment outcomes." (PMID 39459201, 2024). "Additionally, although XPO1 is often overexpressed in cancers and is responsible for carrying a broad range of proteins and mRNA species, our correlation results suggest that it is the cargo which XPO1 transports that is of importance—rather than XPO1 itself—in determining therapeutic effectiveness." (PMID 39682167, 2024). "Therefore, the accumulation of NFKBIA within the nucleus due to XPO1 inhibition in TNBC cells may explain the reduction in NF-kB transcriptional activity similar to that seen in other cancer contexts." (PMID 39682167, 2024).
cancer (continued). "Therefore, XPO1 is a potential therapeutic target for malignant tumors." (PMID 37754264, 2023). "Remarkably, PLK1 and XPO1 have been reported to be selectively required for KRAS-mutant cancers by counteracting mitotic and nuclear export stress associated with KRAS-induced tumorigenesis, and our recent study has implicated PLK1 in metabolic stress response of KRAS-mutant cancers." (PMID 35039048, 2022). "The overall distribution of XPO1-mutated patients in this cohort and their association with other high-risk CLL co-factors falls in line with previous reports for this mutation, providing further evidence for the E571 XPO1 mutation as a cancer-associated genetic abnormality." (PMID 33451349, 2021). "Thus, the inhibition of XPO1 is a promising therapeutic strategy for cancer treatment." (PMID 31371628, 2019). "However, how XPO1 expression is up-regulated in cancer cells is unclear." (PMID 31382411, 2019). "Hence, XPO1 has become a promising target in cancer therapy." (PMID 31088931, 2019). "Even though the b-LMB based assay successfully correlated occupancy of XPO1 to dosing level in PBMCs from mice and in cancer cells in culture, it could only measure the drug-target interaction in viable cells, which was not a feasible source of biopsy material from patients." (PMID 29299164, 2017). "Since XPO1 controls the cellular localization of multiple tumor suppressor proteins (TSPs) simultaneously, inhibition by selinexor blocks signal transduction pathways and results in cell cycle arrest, lack of cellular proliferation and induction of apoptosis in cancer while sparing normal cells." (PMID 29137251, 2017). "We therefore hypothesized that a combination of the XPO1 inhibitor KPT-185 andselective mTORC1/2 dual inhibitor AZD-2014 would demonstrate synergistic inhibition of MCL cell growth by repressing prosurvival metabolism in this cancer." (PMID 28388555, 2017). "Our studies indicate that cancer cell response to selinexor therapy is determined by pathways downstream of XPO1 inhibition, and in at least 4 out of 7 selinexor resistant cell lines, could also be determined by overexpression of the XPO1 target." (PMID 26654943, 2016). "Therefore, blocking XPO1 nuclear export may sensitize cancer cells either by preventing export of additional tumor suppressors or by preventing cell cycle progression." (PMID 25476752, 2014). "Using two-box analysis of The Cancer Genome Atlas (TCGA) and Genotype-Tissue Expression (GTEx) databases, we compared the expression levels of XPO, including XPO1, CSE1L, XPOT, XPO5, and XPO6, in each tumor and normal tissue." (PMID 39882192, 2025). "Exportin 1 (XPO1), a nucleartransport protein overexpressed in PDAC, represents a therapeutic vulnerability inKRAS-mutant cancers." (PMID 41394580, 2025). "Exportin-1 (XPO1) is a nuclear export protein that, when overexpressed, can facilitate cancer cell proliferation and survival and is frequently overexpressed or mutated in cancer patients." (PMID 40291981, 2025). "For example, YAPoff cancers are highly sensitive to inhibitors of BCL2-family proteins, NAMPT, XPO1, Aurora kinases, and HDACs." (PMID 40440076, 2025). "Effective implementation of XPO1 inhibitors in NSCLC requires a biomarker-guided approach, as genetic and cancer-subtype contexts strongly influence therapeutic response." (PMID 41440011, 2025). "Compounds like LMB and clinically utilized anti-cancer agents, selective inhibitor of nuclear export (SINE), target Cys528 in Xpo1." (PMID 39899539, 2025). "While the downregulated DEGs in the Control vs. Poly I: C treated group of Gaddi dogs showed pathways highlighting, such as in cancer with NOTCH2, MDM2, and E2F3, the pathway related to RNA metabolism was also enriched for genes such as HNRNPA3 and XPO1." (PMID 40621499, 2025).
cancer (continued). "XPO1 promotes the expression of genes involved in the epithelial−mesenchymal transition (EMT), a process that allows cancer cells to acquire migratory and invasive properties, inducing metastasis." (PMID 40507356, 2025). "Various studies have highlighted that nuclear transport receptors including XPO1, KPNA2, and KPNA4, exhibit hyperactivity in cancer and facilitate the export of vital tumor suppressors to the cytoplasm or the import of oncogenes to the nucleus." (PMID 38820302, 2024). "Selinexor (an inhibitor of XPO1), the most prominent member of the SINE compound group, has been extensively evaluated in phase I and II clinical trials for various cancers." (PMID 38783482, 2024). "For this reason, XPO1 can serve as a target for diagnosing and treating OSCC, as well as pan‐cancer." (PMID 39177040, 2024). "Exportin-1 (XPO1) is a primary component of the nuclear export pathway and is overexpressed in almost all cancers." (PMID 39580422, 2024). "The clinical approval of selinexor, a specific inhibitor of exportin-1 (XPO1), marks the first nuclear protein inhibitor, fully demonstrating the importance of nuclear transport pathways in cancer therapy." (PMID 39404930, 2024). "We tested the effect of CB6644 (targeting RUVBL1/2 complex), MKT077 (inhibiting HSPA9), selinexor (blocking XPO1, nuclear exportin), and MeAIB (targeting SLC38A2) on cell lines representing three different cancer types versus the normal fibroblasts." (PMID 39217152, 2024). "More importantly, we identify several MYC-SL genes in the RNA transport pathway, apart from XPO1, which are yet to be targeted and can serve as rational, and specific targets against MYC-driven cancers." (PMID 38302473, 2024). "SINE compounds, such as selinexor, that are potent XPO1 inhibitors are able to simultaneously target numerous pathways in NHL cells, leading to cytotoxic effects and sensitization to other anti-cancer agents." (PMID 36671496, 2023). "Both in vitro and in vivo, we demonstrated that the approved XPO1 inhibitor drug selinexor enhances the replication of MYXV and kills diverse human cancer cells." (PMID 37377603, 2023). "Selinexor is an exportin-1 (XPO-1) inhibitor that forces the nuclear retention and functional activation of tumor suppressor proteins, thereby inducing apoptosis in cancer cells." (PMID 36576532, 2023). "Exportin-1 (XPO1) is a key player in the nuclear export pathway and is overexpressed in almost all cancers." (PMID 36671496, 2023). "FOXO3a, a recognised nuclear export cargo of exportin 1 (XPO1), is a transcription factor that has been shown to play a significant role in the progression of various cancers, including PDAC." (PMID 38131168, 2023). "We performed an in silico analysis to identify cancer genes whose mRNA levels positively correlate with those of XPO1, the gene coding for CRM1 in various solid tumours and AML patients." (PMID 37046649, 2023). "This is further supported by studies finding that XPO1 inhibition using SINE compounds restores nuclear localization of tumour suppressor proteins and sensitizes the cancer cells to chemotherapy." (PMID 36671496, 2023). "This mutation located in the nuclear export signal (NES)-binding groove of XPO1 protein and was suggested to affect the binding preferences of XPO1 for nuclear export protein and RNA19,22,44,45, and play an oncogenic role in cancer." (PMID 35347147, 2022). "In this study, we investigated the biological function of XPO1 in GBC and the anti-cancer effects of the XPO1 inhibitor, KPT-330." (PMID 36180918, 2022).
cancer (continued). "XPO1, one of the exportins identified, has been found to be a druggable vulnerability in KRAS-mutant cancer cells." (PMID 35839996, 2022). "To clarify the expression of XPO1 in GBC, we first examined its mRNA level in 35 pairs of GBC and adjacent non-cancer tissues by the qRT-PCR." (PMID 36180918, 2022). "Since the release of HMGB1 plays an important role in shaping the tumor immune microenvironment, it is also expected that XPO1 can promote the translocation and release of HMGB1 in cancer." (PMID 35217834, 2022). "Selinexor and eltanexor are selective inhibitor of nuclear export (SINE) compounds that specifically inhibit the exportin-1 (XPO1, or CRM1) protein, a karyopherin that is often upregulated in human cancers." (PMID 36059685, 2022). "Targeting XPO1 with selinexor has demonstrated promising results in clinical trials, leading to FDA approval of its use for multiple relapsed/refractory cancers." (PMID 34944778, 2021). "Exportin-1 (XPO1) is a nuclear exporter, which mediates nuclear export of various cancer inhibitors." (PMID 32742495, 2020). "Currently, the dominant XPO1 inhibitor, selinexor (KPT-330) and its related analog altenexor, are being assessed in several phase I-II clinical trials for different cancers." (PMID 31052304, 2019). "In this study, we show that the orally bioavailable XPO1 inhibitor KPT-330 reduced Mcl-1 protein level, by which it synergized with Bcl-xL inhibitor A-1331852 to induce apoptosis in cancer cells." (PMID 31113936, 2019). "Due its XPO1 inhibitory effects, LMB was also shown to be a potent cell cycle arrest inducer and apoptosis inducer in cancer cells." (PMID 29735942, 2018). "XPO1 is a nuclear exporter overexpressed in AML cells and its inhibition decreases Mcl‐1 levels in cancer cells." (PMID 30596398, 2018). "Exportin 1 (XPO1) mediates nuclear export of numerous molecules, including oncogenic transcription factors, ribosomal subunits, and RNAs, and is critical for cancer survival and proliferation." (PMID 28388555, 2017). "Selective Inhibitor of Nuclear Export (SINE) compounds are a family of small-molecules that inhibit nuclear export through covalent binding to cysteine 528 (Cys528) in the cargo-binding pocket of Exportin 1 (XPO1/CRM1) and promote cancer cell death." (PMID 26654943, 2016). "In an effort to target this dysfunctional mechanism common to many cancer types, Karyopharm Therapeutics has developed Selective Inhibitor of Nuclear Export (SINE) compounds which bind to and inhibit XPO1 function." (PMID 26654943, 2016). "The orally bio-available small-molecule XPO1 inhibitors called selective inhibitor of nuclear export (SINE) compounds, have proven anti-cancer activity in hematological and solid cancers, while sparing normal cells and showing limited off-target complications." (PMID 27634897, 2016). "The nuclear export protein, exportin-1 (XPO1/CRM1), is overexpressed in many cancers and correlates with poor prognosis." (PMID 27713151, 2016). "This study provides evidence that the novel orally bioavailable XPO1 inhibitor KPT-335 is safe and exhibits activity in a relevant, spontaneous large animal model of cancer." (PMID 24503695, 2014).
cancer (continued). "We found that KLF5 did not affect E2F1 expression, and therefore, we suggest that KLF5 may play a part in promoting cancer by inactivating RB1 by regulating the expression of Cyclin D 1 and XPO1." (PMID 39888288, 2025). "Not surprisingly, high expression of XPO1 is correlated with poor clinical outcomes across a range of cancer types." (PMID 40291981, 2025). "It is also likely that there will not be just one treatment for each class, but rather that defining a cancer as either YAPon or YAPoff will direct you towards a subset of drugs - e.g., kinase or YAP/TEAD inhibitors for YAPon cancers and BCL2, XPO1, NAMPT or epigenetic inhibitors for YAPoff cancers." (PMID 40440076, 2025). "XPO1 as a potential therapeutic target specifically for MYC-driven cancers has not been previously recognized." (PMID 38302473, 2024). "As a proof-of-principle, we targeted one of the nuclear to cytoplasmic transport genes, XPO1, demonstrating its inhibition induced tumor cell death both in vitro and in vivo, in mouse and human MYC-driven cancer cell lines, in a transgenic mouse model of MYC-driven HCC, and in human HCC PDX." (PMID 38302473, 2024). "Moreover, XPO1 and PIK3CA inhibitors, currently approved for the treatment of various cancer types, hold potential for repurposing as therapeutic agents for PD86,87." (PMID 39711693, 2024). "The nuclear export protein XPO1 has emerged as a potential therapeutic target in cancer, but its role in TNBC has not been fully characterized." (PMID 39682167, 2024). "We show here that inhibition of XPO1-mediated nucleocytoplasmic transport blocked growth in vitro, induced tumor regression in vivo in a transgenic mouse, and inhibited human HCC PDX, more effectively in MYChigh cancers." (PMID 38302473, 2024). "This mandates a search for targetable signatures, such as RUVBL1, HSPA9, and XPO1, whose redundancy is limited by directly non-overlapping roles in cancer cell metabolism." (PMID 39217152, 2024). "While selective inhibitors of XPO1 have already been approved for adjuvant therapy in other cancers, inhibitors for RAN and RPRD1B1 have not yet been developed." (PMID 38804617, 2024). "In contrast, studies in Xenopus oocytes and human cancer cells found no role for the Crm1 homologue, Xpo-1, in tRNA nuclear export." (PMID 36099418, 2022). "Active nuclear export of TSPs and eIF4E-bound oncoprotein mRNAs was effectively blocked by SINE compounds which selectively inhibit XPO1 function, leading to nuclear retention of TSP and eIF4E-bound mRNAs, impeding the cancer growth and prompting selective apoptosis of cancer cells." (PMID 34562230, 2022). "Furthermore, XPO1 and CAS have different cargoes, and this formulates a rationale for personalized therapy in different cancers." (PMID 35013112, 2022).